ETV5 (ETS variant transcription factor 5)
Diseases named in the same sentence as ETV5 in open-access papers (continued):
Sharing a sentence is not in itself a finding about the gene and the disease.
tumor (continued). "The updated molecular mechanisms of ETV5 in cancer biology and tumor progression are delineated." (PMID 36872348, 2023). "Furthermore, the expression level of ETV5 was not only correlated to tumor stage and ESCC metastasis from the IHC results, but also correlated to overall survival." (PMID 35813298, 2022). "Moreover, we investigated the correlation of ETV1 and ETV5 with tumor-infiltrating immune cells (TIICs) in CRC tumor microenvironments via the Tumor Immune Estimation Resource (TIMER) and Gene Expression Profiling Interactive Analysis (GEPIA)." (PMID 35860243, 2022). "Furthermore, overexpression of ETV5 has been correlated with higher malignancy in multiple human tumour types including PCa, where it is present in a fusion with the TMPRSS2 gene." (PMID 35472129, 2022). "ETV5 accelerates tumor growth by promoting cell cycle G1/S transition in colorectal cancer." (PMID 35813298, 2022). "The colony formation assay also confirmed that ETV5 promotes tumor proliferation." (PMID 33931578, 2021). "Previous studies have also confirmed that ETV5 promotes tumor proliferation." (PMID 33931578, 2021). "More research has found that ETV5 participates in tumor oncogenesis and progression." (PMID 33931578, 2021). "Further, we observed higher expression of ETV5 in the proximal tumor as compared to the distal tumor in all three (CIT, GSE14333 and GSE72970 cohorts) which is in accordance with more aggressive and high-grade histology of proximal tumors compared to distal tumors." (PMID 33658938, 2020). "GSEA and additional assays confirmed that ETV5 could promote angiogenesis by inducing the secretion of another tumor angiogenesis factor (CCL2) in CRC cells to facilitate Bevacizumab resistance." (PMID 33099574, 2020). "Combined antiCCL2 and antiVEGFA (Bevacizumab) treatment could inhibit tumor angiogenesis and growth more effectively than single treatments in CRCs with high expression of ETV5 (ETV5+ CRCs)." (PMID 33099574, 2020). "This suggests that the effect of ETV5 upregulation in bladder cells may differ depending on tumour sub-type." (PMID 30952872, 2019). "Because the expression of Etv5 targets in the tumor may reflect the expression of these genes in different cell types, we queried an established brain cell type-specific transcriptome database." (PMID 29787563, 2018). "The Hec1A-ETV5 overexpression model has been extensively used to mimic the process of tumor invasion in EEC, as ETV5 overexpression is known to induce EMT in EEC and has been reported at the invasive front of EEC tumors, promoting migration and invasion in vitro and in vivo." (PMID 29682175, 2018). "Next, we sought to determine whether the target genes of Etv5, which were differentially expressed in the tumor, are similarly differentially expressed in tumor-bearing optic nerves relative to normal healthy non-neoplastic optic nerve." (PMID 29787563, 2018). "Interestingly, they include EGR1, ETV4, ETV5 and FosB that have been associated with EMT and tumour aggressiveness in several cancers." (PMID 28651004, 2017). "Thus, ETV4 and ETV5 may act as key downstream effectors of BRD4 to promote tumor growth and dictate BETi efficacy." (PMID 36475791, 2022). "Additionally, in vivo study showed knockdown of ETV5 inhibited tumor metastasis." (PMID 35813298, 2022). "Consistent with our research results, ETV5 is overexpressed in various malignant tumors, including OC, and involved in tumor cell angiogenesis, migration, invasion, and other malignant biological behaviors, suggesting that ETV5 may serve as a potential molecular therapeutic target for HGSOC." (PMID 34736492, 2021). "In the context of cancer progression, where uncontrolled migration of and invasion by tumor cells is a pivotal feature, this effect of LPP on ETV5-dependent gene expression may reinforce epithelial-to-mesenchymal transition and expansion of the tumor into neighboring tissues." (PMID 34867475, 2021).
tumor (continued). "For this, we compared the extent of metastasis resulting from the intracardiac injection of both naïve Hec1A cells, and ETV5 over-expressing Hec1A cells, further modified to constitutively express the luciferase reporter gene and allow vital bioluminescent imaging of disseminating tumor cells." (PMID 25261936, 2014). "ETV4 and ETV5 of the ETS family are involved in cancer stemness and metabolic reprogramming, whereas TNFRSF14 inhibits tumor growth through apoptotic signaling." (PMID 41304759, 2025). "ETV5, belonging to the ETS family of transcription factors, is a key factor in cancer research, recognized for its role in cell cycle regulation and tumor progression." (PMID 38515748, 2024). "The increased tumor size and lung metastatic foci induced by YTHDF2 overexpression were reversed after ETV5 was downregulated." (PMID 38247171, 2024). "Tumour infiltrating lymphocyte and myeloid populations were enriched for motifs including ETS family transcription factors (ETV5/6 and EHF) and MEF2B, as well as NFKB1 which is a central activator of pro-inflammatory genes." (PMID 39341888, 2024). "The knockdown of IGFBP5 expression in 772 GSCs suppressed GSC invasion, as well as the expression of the target genes ETV5 and FBXW9, and tumor volume, while significantly prolonged the survival of the mouse." (PMID 36949068, 2023). "We next examined the degree of MAPK pathway inhibition after treatment in tumor cells using an MAPK gene expression signature score based on changes in the MAPK-regulated transcripts (DUSP6, ETV4, ETV5 and SPRY4) in tumor epithelial cells." (PMID 36702949, 2023). "ETV1, ETV4, and ETV5 comprise the PEA3 transcription factor subfamily and were found to be significantly related to numerous tumor markers." (PMID 35860243, 2022). "We determined that three oncogenes, PD-L2, ETV5, and MTOR and 113 long intergenic non-coding RNAs (lincRNAs) were constantly up-regulated, whereas two oncogenes, BCR and GTF2I, one tumor suppression gene MEN1, and 30 lincRNAs were constantly down-regulated." (PMID 35317849, 2022). "Other genes, such as ETV4, ETV5, CCND1, EPHA2, and EPHA4, also play a role in activating the MAPK pathway, promoting tumor resistance to MEKi." (PMID 36437939, 2022). "ETV5, consistent with other ETS family members, is an oncogenic transcription factor, involved in regulating multiple processes in tumor progression and metastasis, such as EMT, invasion, migration, cell cycle, and apoptosis, and chemotherapy resistance." (PMID 34736492, 2021). "However, whether ETV5 regulates the tumor cell cycle remains unclear." (PMID 33931578, 2021). "Within the tumor tissues, the RKO/ETV5+Bev group exhibited higher expression of VEGFA and CD31 than that exhibited by RKO/Vector+Bev group." (PMID 33099574, 2020). "Therefore other molecular changes may drive an upregulation of ETV5 in FGFR3-wild type tumours." (PMID 30952872, 2019). "ETV5 belongs to the ETS transcription factors family, involved in various processes such as cytokine production or migration of tumor cells." (PMID 29963229, 2018). "Extensive search of the literature revealed a potential key role of genes at the identified porcine loci in tumor invasion (DST, PLEKHA5, CBY1, LIMK2 and ETV5) and immune response modulation (ETV5, HERC3 and DICER1) of the progression phenotypes." (PMID 29963229, 2018). "Then, we conducted SCENIC analysis to explore the transcriptional regulation driving the acquisition of the cholesterol-related Tumor-Modifying state in neutrophils which revealed activation of BHLH family transcription factors (BHLHE40, ETV5, OLIG2, and SREBF1) within the Neu-T-CCL3 cluster." (PMID 38822440, 2024). "After the tumor metastasis assay was performed, we found TAOK3 or ETV5 or IRGM knockdown could robustly reduce the average number of lung metastasis nodules and the size of metastasis nodules indicated by HE staining." (PMID 37705061, 2023).
tumor (continued). "However, from a prognostic perspective, CD5, SLCO1B1, and CD79A have been demonstrated to have protective value in various tumors, whereas ETV5, FZD7, SNX7, and SLC1A7 are involved in tumor progression." (PMID 37680641, 2023). "In addition, separation between LCH cells and other lesion MNPs was also evident on the regulatory network level, that revealed neoplasm/cancer related regulons specifically active in LCH cells (ERG1, ETV5, ZMIZ1)." (PMID 36525505, 2022). "Previous studies support that ETV5 promotes tumor proliferation, but cell cycle changes have not yet been described in detail." (PMID 33931578, 2021). "Unfortunately, ETV5 of the PEA3 subfamily does not appear to be significantly altered in tumor vs. non-tumor samples in the microarray datasets used in this study (data not shown)." (PMID 33671331, 2021). "Furthermore, ETV5 has been reported to directly influence the transcription of MMP2 and TIMP to modify tumor growth." (PMID 33099574, 2020). "Taken together, these observations argue that differential Etv5 expression reflects a “whole tumor” property, rather than representing the individual contributions from any single cell type within the tumor." (PMID 29787563, 2018). "Similar to the results obtained from 3-month-old mouse specimens, there was differential Etv5 RNA-Seq expression in 6-week-old optic glioma-bearing mice, which contain a developing, but not mature, tumor." (PMID 29787563, 2018). "Consistent with the RNA-seq data, Etv5 expression was detected in the tumor-bearing optic nerves, but not in their non-neoplastic counterparts." (PMID 29787563, 2018). "Western blot analysis of explanted tissue could not reliably detect CIC::DUX4 protein expression in any tumor sample but did reveal increased ETV5 levels in full-length CIC::DUX4 tumors compared with EV or dC1 tissue." (PMID 39530749, 2024). "In summary, ETV5 and its ETS family members can directly participate in the occurrence and development of tumors, or participate in tumor progression and metastasis by regulating the expression of key molecules involved in the process of tumor malignant transformation." (PMID 34736492, 2021). "This suggests that the role of ETV5 in bladder carcinogenesis may not be limited to FGFR3-mutant tumours but may also be relevant to tumours with other alterations resulting in MAPK/ERK activation, such as RAS mutations." (PMID 30952872, 2019). "While at the superficial tumor, uncleaved ALCAM maintained a correlation with the major adhesion complex E-Cadherin/β-catenin; at the invasive tumor, where a more mesenchymal microenvironment takes place, it correlated with COX-2, SNAIL, MMP-9 and ETV5 mesenchymal markers." (PMID 29682175, 2018). "Moreover, ETV5 has been shown to co-localize with MMP-2 and -9 at the invasive front of the tumor." (PMID 29682175, 2018). "Importantly, differential Etv5 and Etv5 network expression was not directly the result of Nf1 gene dysfunction in specific cell types, but rather reflects a property of the tumor as an aggregate tissue." (PMID 29787563, 2018). "In addition to RNA-Seq experiments, we also used quantitative real-time PCR (qPCR) to analyze Etv5 RNA expression in independently-generated non-neoplastic (Nf1flox/flox; abbreviated N for normal) and tumor-bearing (Nf1flox/null GFAP-Cre; “OPG-1”) optic nerves." (PMID 29787563, 2018). "From the Oncomine database, multiple tumor types including CRC demonstrated higher ETV4 and ETV5 expression in tumor tissues than those in corresponding normal tissues." (PMID 35860243, 2022). "WT CIC is a transcriptional repressor discovered in Drosophila which is involved in developmental processes and acts as a tumor and metastasis suppressor predominantly through the repression of PEA3 (ETV1, ETV4, and ETV5) family members and negative MAPK pathway (DUSP4/6) regulators." (PMID 39530749, 2024).
cancer (48 papers, 2010 to 2025). A tumor composed of atypical neoplastic, often pleomorphic cells that invade other tissues. "The increased expression of ETV5 in cancers was found to be associated with clinicopathological features and patient prognosis, indicating its potential application as a diagnostic and prognostic biomarker." (PMID 36872348, 2023). "ETV4 and ETV5 have been previously implicated in mediating progression of disease in a variety of cancer systems." (PMID 36509998, 2023). "In order to identify the molecular mechanism underlying the ETV5-mediated increase in cancer progression, RNA-seq analysis was performed to compare protein-coding transcripts levels in ECA109, KYSE150 and TE1 cells treated with or without siETV5." (PMID 35813298, 2022). "ETV5 has been implicated in proliferation in different type of cancer cells." (PMID 37876309, 2023). "Finally, we delineated the effects of ETV5 on multiple hallmarks of cancer cells, and proposed it as a potential diagnostic biomarker, as well as a therapeutic target, for further translational research." (PMID 36872348, 2023). "Additionally, ETV5 is linked to the maintenance of cancer stem cell (CSC) phenotype in breast cancer." (PMID 35813298, 2022). "Our observations indicate that the MAPK/COP1/ETV5 axis plays an important role in regulating transcriptional outputs in ERK-dependent cancers." (PMID 40643496, 2025). "Changes in down-regulated genes were ETV4 (ETS Variant Transcription Factor 4) and ETV5 (ETS Variant Transcription Factor 5) are related to transcriptional regulation, EML4 (EMAP like 4), BCL2 and Myc are related to cancer development." (PMID 39834948, 2024). "In colon cancer, ETV1 and ETV5 expression levels are positively correlated with infiltration of CD8+ T cells, CD4+ T cells, macrophages, DCs, and cancer-associated fibroblasts." (PMID 39337492, 2024). "Gene mutation, post-transcriptional modification and molecular signaling crosstalk all contribute to the dysregulation of ETV5 in cancers and physiological processes." (PMID 36872348, 2023). "ETV5 displayed higher expression in many types of cancers compared to matched normal tissues, and its expression was a predictor of poor survival." (PMID 36872348, 2023). "ETV5 activation contributes to many oncogenic and metastatic features of cancer cells, including proliferation, mobility, invasiveness, angiogenesis, and drug resistance." (PMID 36872348, 2023). "ETV5 also plays critical roles in the formation and development of various cancers, affecting virtually all hallmarks of cancer cells, including the epithelial–mesenchymal transition (EMT), angiogenesis, cell cycle, oxidative stress and drug resistance." (PMID 36872348, 2023). "Cancer cells with activated Ras signaling stabilize ETV5 protein through enhanced DET1 phosphorylation at Ser458, which inhibits the degradation of ETV5." (PMID 36872348, 2023). "Cancer cells with downregulated ETV5 exhibited reduced adhesion to collagen type I, collagen type IV, fibronectin, and laminin." (PMID 36872348, 2023). "The ETV5 has been reported to be overexpressed in different types of human cancer and its involvement in cell proliferation has been proven." (PMID 37876309, 2023). "Here, we reported that variations in ETV1, ETV4, and ETV5 expression level correlated with prognosis in different types of cancer including CRC." (PMID 35860243, 2022). "i3 cancers showed higher expression of downstream MAPK components (DUSP4 and ETV5) and i2 cancers had overexpression of EGFR ligands, AREG and EREG." (PMID 35773407, 2022). "Recently, ETV5 attracts much attention for its potential role as an oncogenic transcription factor involved in multiple cancers." (PMID 35813298, 2022). "Recently, ETV5 has attracted much attention for its important role as an oncogenic transcription factor in multiple cancer types and its involvement in multiple biological processes." (PMID 35813298, 2022).
cancer (continued). "Recent studies have found that ETV5 is overexpressed in several malignant tumors, such as OC, inducing transcription of multiple oncogenes involved in cell apoptosis resistance, angiogenesis, migration, invasion, and other malignant biological behaviors." (PMID 34736492, 2021). "It was reported that ETS variant transcription factor 5 (ETV5), a key member of the ETS family, mainly plays a role as an potential oncogene in various malignant tumors." (PMID 34736492, 2021). "Either mutations in or loss of CIC can promote cancer progression via upregulating the expression of PEA3 group genes (ETV1/ER81, ETV4/PEA3, and ETV5/ERM), the best characterized and reliable CIC target genes." (PMID 32042269, 2020). "Given the importance of activated ALK signalling and since ALK fusion genes also achieve enhanced signalling in ALCL and NSCLC, we investigated ALK-induced ETV5 expression in these cancer entities." (PMID 31937834, 2020). "In summary, our data indicate that ETV5 regulation by activated ALK is a conserved feature across different cancer and cell types." (PMID 31937834, 2020). "ETV5 is an oncogenic member of the ETS transcription factor family, associated with cell proliferation and metastasis in various cancers, and a known target of thyroid-specific transcription factor FOXE1." (PMID 24138990, 2013). "Similarly, ETV5 contributes to processes such as cell proliferation, differentiation, and tissue repair, making it a key factor in cancer progression, embryonic development, and tissue repair." (PMID 40536817, 2025). "Studies have shown that ETV1, ETV4, and ETV5 are highly expressed in a variety of cancers." (PMID 39668941, 2025). "High expression of ETV5, similar to ETV1, indicates advanced stage and poor prognosis of CRC patients, mainly due to correlation with increasing immune infiltration with EMT-inducing M2 macrophages and cancer-associated fibroblasts (CAFs)." (PMID 39596218, 2024). "Interestingly, ETV5 is mostly upregulated in cancers, with rarely being downregulated in some cases." (PMID 36872348, 2023). "In addition, ETV5 is repeatedly found to be overexpressed in multiple malignant tumors, where it is involved in cancer progression as an oncogenic transcription factor." (PMID 36872348, 2023). "Mutations and loss of CIC have been reported to promote the progression of various cancers via derepression of cancer-associated CIC target genes, including polyomavirus enhancer activator 3 (PEA3) group genes (ETS variant transcription factor 1 [ETV1], ETV4, and ETV5)." (PMID 36619173, 2022). "Furthermore, by analyzing the correlation of clinicopathologic parameters with ETV5 level in ESCC tissues, we found that ETV5 protein level was higher in Stage III-IV cancers than in Stage 0-II cancers." (PMID 35813298, 2022). "We further studied the effect of ETV5 on cancer metastasis by mice modes." (PMID 35813298, 2022). "Notably, the major PEA3 group members (e.g., ETV1, ETV4, or ETV5) regulated by CIC differ among cancer cell types; the expression of ETV5 and ETV4 is most highly and significantly upregulated by CIC deficiency in PC and HCC cell lines, respectively." (PMID 32238859, 2020). "Subsequently, we looked at whether ETV5 knockdown mediates the oncogenic effect of mutant FGFR3 in cancer cells." (PMID 30952872, 2019). "We consolidated these findings with RISH assays for Etv5, a transcriptional target of the RAS-MAPK pathway activated by FGF in development and cancer." (PMID 39817451, 2025). "ETV5 also directly transcriptional regulates MMP2 expression and gelatinase activity, which confer an invasive phenotype on cancer cells." (PMID 36872348, 2023). "Expression of endogenous retroviruses envelope protein in different human cancer cell lines was observed to induce the transcription of ETV4 and ETV5, which are downstream effectors of the MAPK ERK1/2." (PMID 37234529, 2023).